EBI3 (Epstein-Barr virus induced 3)
Description:
Associates with IL27 to form the IL-27 interleukin, a heterodimeric cytokine which functions in innate immunity. IL-27 has pro- and anti-inflammatory properties, that can regulate T-helper cell development, suppress T-cell proliferation, stimulate cytotoxic T-cell activity, induce isotype switching in B-cells, and that has diverse effects on innate immune cells. Among its target cells are CD4 T-helper cells which can differentiate in type 1 effector cells (TH1), type 2 effector cells (TH2) and IL17 producing helper T-cells (TH17). It drives rapid clonal expansion of naive but not memory CD4 T-cells. It also strongly synergizes with IL-12 to trigger interferon-gamma/IFN-gamma production of naive CD4 T-cells, binds to the cytokine receptor WSX-1/TCCR. Another important role of IL-27 is its antitumor activity as well as its antiangiogenic activity with activation of production of antiangiogenic chemokines.
Synonyms: IL-27B; IL27B; IL35B
Tractability: Antibody: UniProt places it where antibodies can reach, with high confidence; its Gene Ontology location is reachable by antibodies, with high confidence; UniProt predicts a signal peptide or a membrane-spanning region.
Gene: Protein-coding gene on chromosome 19 (4,229,314 to 4,237,528, forward strand). Ensembl gene ENSG00000105246.
Subcellular location: Secreted
Pathways (Reactome):
Immune System: Interleukin-27 signaling; Interleukin-35 Signalling
Gene Ontology:
Molecular function: cytokine receptor activity; protein binding; interleukin-27 receptor binding
Biological process: regulation of T cell proliferation; cell surface receptor signaling pathway via JAK-STAT; humoral immune response; interleukin-27-mediated signaling pathway; interleukin-35-mediated signaling pathway; negative regulation of apoptotic process; negative regulation of T-helper 1 type immune response; positive regulation of alpha-beta T cell proliferation; positive regulation of interleukin-10 production; positive regulation of MAPK cascade; positive regulation of type II interferon production; regulation of B cell proliferation; T cell proliferation; T-helper 1 type immune response; immune system process
Cellular component: extracellular region; interleukin-35 complex; receptor complex; endoplasmic reticulum lumen; plasma membrane; membrane
Genetic constraint (gnomAD): Loss-of-function variants: 19 observed, 20.31 expected, observed/expected ratio (o/e) 0.94, 90% interval 0.65 to 1.37. The upper end of that interval is the gene's LOEUF score, 1.37, which puts it in group 5 of 6, group 1 being the genes least tolerant of losing a copy. Missense variants: 331 observed, 294.29 expected, observed/expected ratio (o/e) 1.12, 90% interval 1.03 to 1.23. Synonymous variants: 154 observed, 125.32 expected, observed/expected ratio (o/e) 1.23, 90% interval 1.08 to 1.4.
Homologues: Orthologues: chimpanzee EBI3 (99% identical), dog EBI3 (73% identical), pig EBI3 (72% identical), guinea pig EBI3 (61% identical), mouse Ebi3 (61% identical), rat Ebi3 (60% identical), tropical clawed frog ebi3 (38% identical), zebrafish ebi3 (31% identical). Paralogues in human: CNTFR (30% identical), IL11RA (28% identical), CSF3R (24% identical), IL12RB2 (20% identical), IL6ST (20% identical), IL6R (18% identical), IL31RA (18% identical), IL27RA (17% identical), OSMR (17% identical), LEPR (16% identical), LIFR (16% identical), GHR (16% identical), and 11 more.
Diseases named in the same sentence as EBI3 in open-access papers:
EBI3 is named in the same sentence as 106 diseases in open-access papers, as found by Europe PMC text mining. Sharing a sentence is not in itself a finding about the gene and the disease. The quoted sentences say what the papers report.
lung carcinoma (10 papers, 2013 to 2023). "Ebi3 expression in lung cancer cells has also been found to be associated with tumor progression and siRNA-mediated down-regulation of the Eib3 gene inhibited proliferation of lung cancer cells." (PMID 28794689, 2017). "It was demonstrated that high expression of EBI3 in lung cancer patients is associated with a poor prognosis and that serum levels of EBI3 in lung cancer patients are significantly higher than those in healthy volunteers." (PMID 27867385, 2016). "Thus, EBI3 seems to be associated with tumor growth and a highly malignant phenotype of lung cancers." (PMID 34603342, 2021). "It has been reported that the abnormal expression of EBI3 is closely related to the poor prognosis of many malignant tumors, such as lung cancer, colon cancer, and nasopharyngeal cancer, and EBI3 plays different roles in different tumors." (PMID 39291183, 2022). "Inhibition of endogenous EBI3 expression in lung cancer cells by small interfering RNA markedly reduced their growth, while overexpression of exogenous EBI3 in COS-7 monkey kidney cells greatly enhanced their growth." (PMID 34603342, 2021). "The deployment of small interfering RNA (siRNA) directed towards Ebi3 in lung cancer cells was shown to impede lung cancer cell proliferation albeit stable Ebi3 gene expression confers growth promoting activity in vitro and is associated with poor prognosis." (PMID 29641433, 2018). "In human model, it has been shown that EBI3 was expressed in tumor infiltrating dendritic cells, which is a subpopulation of MDSCs, and in lung cancer cells, whereas IL-12p35 was detected in EBI3 tumor cells." (PMID 25356878, 2014). "The subunits of IL-35, EBI3 and IL-12p35, are highly expressed in cancers such as lung cancer, colorectal cancer, and esophageal carcinoma." (PMID 25356878, 2014). "Stable expression of EBI3, a gene that codes for IL-35 subunit, confers growth-promoting activity in lung cancer, whereas small interfering RNA silencing of EBI3 inhibits proliferation of lung cancer." (PMID 25356878, 2014). "Furthermore, suppressed EBI3 expression inhibits lung cancer cell proliferation whereas induction of exogenous EBI3 conferred growth-promoting activity." (PMID 27247488, 2016).
autoimmune disease (8 papers, 2017 to 2023). A disorder resulting from loss of function or tissue destruction of an organ or multiple organs, arising from humoral or cellular immune responses of the individual to their own tissue constituents. "Some studies have explored the relationship between IL-35 (including IL-12 p35 and EBI3) gene SNPs and susceptibility to autoimmune diseases." (PMID 34950136, 2021). "As far as we know, this is the first study explored about the associations between IL-35 gene single nucleotide polymorphisms and the genetic susceptibility to autoimmune diseases, in which IL-35 encoding genes, IL-12A and EBI3, were analyzed together." (PMID 31013577, 2019). "While prolonged maintenance of the stable IL-12p35:Ebi3 complex is desirable for treating an autoimmune disease, it also poses the risk of suppressing antitumor immune responses or compromising the efficacy of vaccines against infectious diseases." (PMID 29051763, 2017). "Thus, the polymorphism of the EBI3 rs4740 may be correlated with the occurrence of autoimmune disease." (PMID 34950136, 2021). "Reportedly, IRE1α is involved in the induction and pathogenesis of autoimmune diseases, thus EBI3 which is upstream of IRE1α may also participate in the pathophysiology of autoimmune diseases." (PMID 36548354, 2022). "The EBI3 subunit played a potential inhibitory role in the development of autoimmune diseases." (PMID 31787974, 2019). "In conclusion, elevated EBI3 may be a potential biomarker for MSC under inflammatory conditions such as RA and it may also be a therapeutic target for IRE1α related autoimmune disease." (PMID 36548354, 2022).
colitis (8 papers, 2013 to 2024). Inflammation of the colon. "By means of knockout mouse models, a deficiency in the IL-35 subunit Ebi3 was shown to play a role in experimental colitis manifestation." (PMID 34069352, 2021). "Compared to C57BL/6 mice, Ebi3−/− mice exhibited more severe colitis symptoms, body weight loss, increased spleen weight, and lower survival rates." (PMID 31955243, 2020). "The in vivo data show that the deficiency of EBI3 plays a key role in colitis manifestation." (PMID 31955243, 2020). "Since UC is a disease with a relapsing–remitting clinical course, epigenetic regulation mechanisms of EBI3 in colitis appeared possible." (PMID 34069352, 2021). "Comparison of colitis manifestations revealed that Ebi3−/− mice developed more severe colitis than C57BL/6, as measured by survival, body weight course, and spleen weight and size." (PMID 31955243, 2020). "Consistently, the data here suggest that histone acetylating conditions, such as upon SAHA application, improve colitis by a mechanism involving the local upregulation of EBI3 and formation of the anti-inflammatory cytokine IL-35 in colon epithelium." (PMID 31955243, 2020). "Our data reveal that EBI3 as the greater inducible subunit of the anti-inflammatory acting IL-35 has a large impact on the HDACi-induced improvement of colitis symptoms." (PMID 31955243, 2020). "First, a chronic DSS colitis model was induced in both, Ebi3−/− mice and the related C57BL/6 wild-type mice; three cycles consisting of 7-day application of DSS to drinking water followed by a washout phase of 14 days." (PMID 31955243, 2020). "Colitis was more distinct in Ebi3−/− compared with C57BL/6 wild-type mice, as seen by more pronounced loss of body weight, increase in spleen weight, and increased mortality." (PMID 31955243, 2020). "As before, colitis was induced in Ebi3−/− and C57BL/6 wild-type mice by three cycles of DSS treatment and additionally treated with SAHA, an HDACi already approved for clinical use." (PMID 31955243, 2020). "As the two possible IL-12 family heterodimers of EBI3, IL-35 and IL-39, exert different effects, the in vivo impact of HDACi on colitis was of interest." (PMID 31955243, 2020). "Taken together, the results presented here indicate a central role of epigenetic EBI3 regulation in colitis." (PMID 31955243, 2020). "This indicates that only B cell derived IL-35 and EBI3 displayed inhibitory effects in colitis." (PMID 36797242, 2023). "Ebi3 deficiency associated with more pronounced negative impacts during inflammatory episodes of colitis progression, as assessed by body weight loss after the first cycle." (PMID 31955243, 2020). "In addition to this, we induced a chronic colitis model in Ebi3−/− mice to examine the epigenetic targeting of EBI3 expression as a possible therapeutic option." (PMID 31955243, 2020). "In conclusion, histone deacetylation of EBI3 plays a key role in colitis manifestation." (PMID 31955243, 2020). "Therefore, EBI3-inducing DNMTi alone or, especially, in combination with HDACi, such as SAHA, might represent a therapeutic option in inflammatory diseases like colitis to alleviate symptoms and prevent colitis-associated cancer development." (PMID 34069352, 2021). "Since EBI3 seems to form the anti-inflammatory dimeric cytokine IL-35, which is able to restrict colitis symptoms, rather than the pro-inflammatory IL-39, increased EBI3 expression may contribute to colitis improvement." (PMID 34069352, 2021). "Our data demonstrate that SAHA-mediated elevation of IL-35 plays a role in this amelioration which was ascertained by treating Ebi3−/− and the corresponding wild-type with SAHA and by comparing colitis manifestation in both strains." (PMID 31955243, 2020).
colitis (continued). "By using a T cell-dependent mouse colitis model in which colitis is induced by adoptive transfer of naive CD4+ T cells into immunodeficient mice, EBI3-deficient naive CD4+ T cells failed to induce colitis with reduced interferon (IFN)-γ production in the intestinal lamina propria lymphocytes." (PMID 34603342, 2021).
colorectal cancer (7 papers, 2014 to 2025). A primary or metastatic malignant neoplasm that affects the colon or rectum. "Our previous reports also found tumor-derived IL-35 or EBI3 associated with IL-12p35 may recruit Treg cells into the tumor microenvironment in favor of tumor growth in human colorectal cancer (CRC)." (PMID 27247488, 2016). "In colorectal cancer, the expression of EBI3, gp130, and pSTAT3 is upregulated, and EBI3 promotes tumor growth through the gp130-STAT3 signaling pathway." (PMID 35719927, 2022). "Tregs obtained from colorectal cancer patients were more capable of inducing EBI3 and P35 expression than those obtained from healthy individuals." (PMID 27682874, 2016). "For instance, METTL14 may promote CD8+ T-cell dysfunction in colorectal cancer through stabilization of Ebi3 mRNA, yet enhance T-cell activation in other contexts by facilitating PDCD1 mRNA degradation." (PMID 41164187, 2025). "Similar trends were similar to those in colorectal cancer, where EBI3 blocking peptide could repress the proliferation of colorectal cancer and tumor growth." (PMID 39726752, 2024). "For quantitative analysis of EBI3, IL-27p28, IL-12p35, gp130, and p-STAT3 expression levels in different types of colorectal cancer tissues, the sections were next scored for immunoreactive area as detailed earlier based on the intensity of staining." (PMID 27247488, 2016). "In this study, firstly we assessed EBI3, IL-27p28, IL-12p35, gp130, and p-STAT3 expression with clinicopathological parameters of colorectal cancer (CRC) tissues; then we evaluated the antitumor T cell responses and tumor growth with a EBI3 blocking peptide." (PMID 27247488, 2016).
Sepsis (7 papers, 2012 to 2025). Sepsis is defined as life-threatening organ dysfunction caused by a dysregulated host response to infection. "For GSE229925, which categorized sepsis patients into groups based on LVEF—high LVEF (HEF, LVEF ≥ 90%), low LVEF (LEF, LVEF < 65%), normal LVEF (NEF, 65% ≤ LVEF < 90%), and sepsis controls—significant differences in EBI3 expression were observed (p > 0.05)." (PMID 40396598, 2025). "In the GSE142615 data set, comparing sepsis patients (control group) to SCM patients (experimental group) revealed a significant difference in EBI3 expression (p < 0.05)." (PMID 40396598, 2025). "Recent studies have further elucidated the roles of key downregulated genes-Ccl4, Ccr7, and Ebi3-in inflammation and sepsis-induced cardiac injury." (PMID 41169382, 2025). "The LOOCV procedure correctly predicted 86% of the SIRS and sepsis classes, and Epstein-Barr virus-induced gene 3 (EBI3) had the highest predictive strength." (PMID 23107287, 2012). "It was however of interest to examine whether monomers and homo-dimers of IL-12p35 and/or Ebi3 can be detected in vivo during inflammatory immune responses of mice to infection, as may occur during sepsis." (PMID 28959012, 2017). "Notably, EBI3, a subunit of IL-27 has been recently unmasked as a potential sepsis biomarker by genome-wide expression profiling." (PMID 24236088, 2013). "The signaling activity of IL‐27 through the IL‐27B (EBI3) receptor protein influences various immune cells, potentially contributing to the immune dysregulation seen in sepsis and SCM." (PMID 40396598, 2025). "EBI3 expression was significantly elevated in SCM compared to sepsis, suggesting its involvement in the progression from sepsis to SCM." (PMID 40396598, 2025). "In the current study, we established the mouse model of sepsis induced by CLP and then detected the level of IL-27 in serum of model mice, as well as the levels of IL-27 subunits (EBI3 and P28) in lung tissue." (PMID 35013123, 2022). "The rationale for investigating IL-27 is based on the observation that EBI3 had the highest predictive strength for bacterial infection of all genes differentially regulated between patients with SIRS and patients with sepsis." (PMID 23107287, 2012).
Autoimmunity (6 papers, 2012 to 2025). The occurrence of an immune reaction against the organism's own cells or tissues. "IL-35 is a key immunosuppressive cytokine composed of the EBI3 and P35 subunits that reduces the autoreactive immune cells and prevents autoimmunity." (PMID 41551875, 2025). "EBI3 dimerizes with IL12p35 to produce IL-35, a regulatory cytokine secreted by Tregs and shown to have potent suppressive function in a variety of conditions, including cancer, autoimmunity, and infections." (PMID 38516885, 2024). "Both Ebi3 and p35 knockout mice show overt autoimmunity or inflammatory disease, suggesting that the EBI3/p35 heterodimer may be an important immunomodulator." (PMID 23285065, 2012).